XRCC6 (X-ray repair cross complementing 6)
Diseases named in the same sentence as XRCC6 in open-access papers (continued):
Sharing a sentence is not in itself a finding about the gene and the disease.
bladder cancer (6 papers, 2011 to 2025). "Although TEX10 positively regulated the XRCC6 level and signaling of Wnt/β-catenin in urinary bladder carcinoma according to this work, the underlying molecular mechanisms involving TEX10, XRCC6, and Wnt/β-catenin channel remain to be further identified." (PMID 34966825, 2021). "Another study also demonstrated that TEX10 (testis expressed 10) promoted radioresistance in urinary bladder carcinoma by stabilising XRCC6 (x-ray repair cross complementing 6), a key factor required for efficient NHEJ upon induction of DNA damage by agents such as ionising radiation." (PMID 36980267, 2023). "In brief, this work revealed that TEX10 could exert a significant carcinogenic effect on urinary bladder carcinoma tumorigenesis and radiotherapy resistance through the activation of XRCC6-related channels." (PMID 34966825, 2021). "Interestingly, we discovered the noticeable relation of TEX10 and XRCC6 in urinary bladder carcinoma that TEX10 promotes the level of XRCC6." (PMID 34966825, 2021). "Therefore, understanding the relationship between various functions of XRCC6 and carcinogenesis of bladder carcinoma may contribute to the development of new anticarcinoma agents against bladder carcinoma." (PMID 34966825, 2021). "Therefore, TEX10 might be a promising radiosensitization drug target for urinary bladder carcinoma treatment via mediating NHEJ impairment via XRCC6." (PMID 34966825, 2021). "Furthermore, this study confirmed that TEX10 silencing inhibited the β-catenin and level activation of cyclin D1 and c-Myc, demonstrating that TEX10 might promote the tumorigenesis of urinary bladder carcinoma via increasing XRCC6 level to enhance the signaling of Wnt/β-catenin." (PMID 34966825, 2021).
lymphoma (6 papers, 2015 to 2025). A malignant (clonal) proliferation of B- lymphocytes or T- lymphocytes which involves the lymph nodes, bone marrow and/or extranodal sites. "Compared to normal B cells, a compelling body of evidence shows that the expression of XRCC6 is downregulated in MM and other lymphoma cells." (PMID 34732266, 2021).
osteosarcoma (6 papers, 2015 to 2022). A usually aggressive malignant bone-forming mesenchymal neoplasm, predominantly affecting adolescents and young adults. "Aberrant expression of XRCC6 is implicated in development of several types of tumors, such as osteosarcoma and cancers of digestive system." (PMID 35836822, 2022). "The mRNA expression level of XRCC6 was measured in osteosarcoma cells and OS samples by quantitative transcription-PCR (qRT-PCR)." (PMID 27455247, 2016). "The expression of XRCC6 protein was measured using Western blot and immunohistochemical staining in osteosarcoma cell lines and patient samples." (PMID 27455247, 2016). "High expression of XRCC6 was correlated with clinical stage and tumor size in osteosarcoma." (PMID 27455247, 2016). "In this paper, we reported, for the first time, that XRCC6 was overexpressed in human osteosarcoma." (PMID 27455247, 2016). "However, the correlation of XRCC6 and human osteosarcoma (OS) is still unknown." (PMID 27455247, 2016).
leukemia (5 papers, 2015 to 2025). A malignant (clonal) hematologic disorder, involving hematopoietic stem cells and characterized by the presence of primitive or atypical myeloid or lymphoid cells in the bone marrow and the blood. "There seems to be a correlation between childhood leukemia and a specific polymorphism in the XRCC6 promoter (T-991C)." (PMID 34732266, 2021). "Likewise, some polymorphisms in both XRCC5 and XRCC6 genes increased the risk of leukemia in a Chinese population." (PMID 34732266, 2021).
liver cancer (5 papers, 2015 to 2024). An epithelial or non-epithelial malignant neoplasm that arises from the liver. "Research demonstrated that DNA damage repair by XRCC6 could reverse TLR4-deficiency-worsened liver cancer development by recovering immunity to support autophagy and senescence." (PMID 33006365, 2020). "Similarly, the genotype of XRCC6 (also named Ku70), could be associated with pterygium risk at T-991C (rs5751129), oral, gastric, kidney, and liver cancer as well as childhood leukemia." (PMID 25705582, 2015). "In this study, we identified three NHEJ genes (FEN1, PRKDC and XRCC6) were upregulated in liver cancer tissue based on TCGA data." (PMID 37016451, 2023). "In the Roessler Liver 2 dataset, high expression of XRCC6 was observed in liver cancer tissues compared with normal adjacent tissues (fold change = 1.828 and P = 1.47E-70, respectively)." (PMID 33006365, 2020).
nasopharyngeal carcinoma (5 papers, 2017 to 2025). A carcinoma arising from the nasopharyngeal epithelium. "The Ku70 promoter T-991C (SNP rs5751129) polymorphism is associated with HCC, gastric, oral, renal, and nasopharyngeal cancer susceptibility, and this novel polymorphism is predicted to lead to differential XRCC6 mRNA and Ku70 protein expression levels." (PMID 28684677, 2017).
ovarian carcinoma (5 papers, 2012 to 2023). A malignant neoplasm originating from the surface ovarian epithelium. "Although a recent transcriptomic study reports high NHEJ activity in OVCAR3 cells, specifically XRCC6 (Ku70) expression was found to be low in the cell line (OVCAR3) compared to the other 12 ovarian cancer cell lines carrying various mutations." (PMID 36899893, 2023). "Interestingly, highly expressed XRCC6 was only linked to prolonged OS for all ovarian carcinoma patients, HR=0.81 (0.7-0.93), P=0.0022, but showed a null association with PFS." (PMID 34539898, 2021).
thyroid cancer (5 papers, 2016 to 2024). "Hence, the aim of this study was to investigate the association between thyroid cancer and three selected polymorphisms (rs2267437, rs5751129, rs132770) in the XRCC6 gene." (PMID 39734356, 2024). "NHEJ- (XRCC6, XRCC5, PRKDC) and HR‐ (SSBP1, SEM1, RPA2, RPA3)-related genes were found to be expressed in both normal follicular and thyroid cancer cells." (PMID 38380364, 2024). "NHEJ- (XRCC6, XRCC5, PRKDC) and HR- (SSBP1, SEM1, RPA2, RPA3) related genes are expressed by both normal follicular and thyroid cancer cells." (PMID 38380364, 2024). "Interestingly, XRCC5 (Ku80), XRCC6 (Ku70) and RAD50 are members of the non-homologous end joining (NHEJ) DNA repair machinery and are recurrently mutated genes in thyroid cancer according to the Catalogue of Somatic Mutations in Cancer (COSMIC) database." (PMID 26870890, 2016).
lung adenocarcinoma (4 papers, 2017 to 2024). A carcinoma that arises from the lung and is characterized by the presence of malignant glandular epithelial cells. "Analysis of the RNA-seq data from The Cancer Genome Atlas data showed that key NHEJ genes such as PRKDC and XRCC6 are expressed at higher levels in lung SqCC compared to lung adenocarcinomas and normal lung tissue." (PMID 28125611, 2017). "In this study, we discovered that XRCC6 is universally upregulated in lung adenocarcinoma, with preliminary bioinformatics analysis indicating its correlation with immune scores and tumor microenvironment scores and enrichment analysis suggesting its association with the cell cycle." (PMID 39769336, 2024).
rectal cancer (4 papers, 2006 to 2025). A primary or metastatic malignant neoplasm that affects the rectum. "Studies have shown that elevated XRCC6 expression can confer radiotherapy resistance in tumor cells, including cervical and rectal cancer cells, potentially diminishing the effectiveness of radiotherapy." (PMID 39769336, 2024). "Proteomic analysis of tissues from rectal cancer patients treated with neoadjuvant chemoradiotherapy revealed the upregulation of RAB5C and X-ray repair cross-complementing proteins 5 and 6 (XRCC5 and XRCC6, also known as Ku70 and Ku80), confirmed also in an in vitro model using irradiated cells." (PMID 40559998, 2025).
Alzheimer disease (3 papers, 2021 to 2022). A progressive, neurodegenerative disease characterized by loss of function and death of nerve cells in several areas of the brain leading to loss of cognitive function such as memory and language. "For example, we found that levels of ADAR, XRCC6 and SBDS were reduced in 5 of 7 Alzheimer’s disease samples and levels of DDX5, U2AF2, ILF3 were reduced in 4 of 7 Alzheimer’s disease NPC vasculature samples by greater than 50%." (PMID 36196083, 2022). "However, many of the RBPs under-expressed in Alzheimer’s disease HPC vasculature do play important roles in neurological health and neurodegenerative diseases including ADAR, XRCC6, U2AF2 and ILF3." (PMID 36196083, 2022).
renal cell carcinoma (3 papers, 2014 to 2017). "Two studies have reported associations with RCC in Chinese population showing polymorphism in the promoter of the BIRC5 gene and variation in the XRCC6 locus, to be the susceptibility candidates for renal cell carcinoma." (PMID 25945350, 2015).
diabetes (2 papers, 2018 to 2025). "Recently, PARP1 and XRCC6 have been proved crucial for fundamental cellular processes, metabolism, ageing, and related diseases, such as cancers, diabetes, neurodegenerative, and cardiovascular diseases." (PMID 29367615, 2018).
male infertility (2 papers, 2017 to 2018). The inability of the male to effect fertilization of an ovum after a specified period of unprotected intercourse. "The mutant GG genotypes and carriers of the CG and GG genotypes of XRCC6 -61C>G showed increased risk for the male infertility." (PMID 28421111, 2017). "The result of current study showed a high association between genetic polymorphism of XRCC6 rs2267437 with male infertility, suggesting that this SNP might be a genetic risk factor for male infertility." (PMID 28421111, 2017). "Furthermore, the G allele of the XRCC6 -61C>G was correlated with increased susceptibility to male infertility." (PMID 28421111, 2017). "It suggests that the mutant allele G of XRCC6 -61C>G could be considered as a risk factor for male infertility susceptibility." (PMID 28421111, 2017). "Furthermore, the G allele of the XRCC6 -61C>G variant was correlated with increased susceptibility to male infertility." (PMID 28421111, 2017). "Large cohort and diverse ethnicity studies as well as further functional analysis are needed to elucidate the biological mechanism of these polymorphisms of XRCC5, XRCC6, and XRCC7 in male infertility." (PMID 28421111, 2017). "In conclusion, this study provided evidences that the XRCC5 VNTR, XRCC6, and XRCC7 6721G>T gene polymorphisms were associated with male infertility risk." (PMID 28421111, 2017). "Our results indicate the association of XRCC5 VNTR, XRCC6 -61C>G, and XRCC7 6721G>T gene polymorphisms with male infertility in Iranian men." (PMID 28421111, 2017). "We evaluate the association between genetic polymorphisms of XRCC5 VNTR, XRCC6 -61C>G, and XRCC7 6721G>T with male infertility susceptibility." (PMID 28421111, 2017). "However, our result showed significant association between XRCC5, XRCC6, and XRCC7 gene polymorphisms and male infertility in an Iranian cohort." (PMID 28421111, 2017). "Since the Ku protein, Ku70 (XRCC6)/80 (XRCC5), and DNA-PKcs (XRCC7) as critical components of NHEJ play important role in DNA integrity of spermatogenesis and can affect the offspring, we hypothesize that genetic variation of these genes may contribute to male infertility risk." (PMID 28421111, 2017).
rectal tumor (2 papers, 2020 to 2024). "Moreover, studies have detected that rectal tumors with a high percentage of Ku70-positive cells (the product of XRCC6, a DNA double-strand repair gene) tended to be radioresistant." (PMID 32784964, 2020).
Azoospermia (1 paper, 2017). Absence of any measurable level of sperm,whereby spermatozoa cannot be observed even after centrifugation of the semen pellet. "With regard to XRCC6 -61C>G, the CG genotype in azoospermia was approximately 2-fold higher than controls, which was significantly different (p = 0.003)." (PMID 28421111, 2017).
cyst (1 paper, 2021). A sac-like closed membranous structure that may be empty or contain fluid or amorphous material. "XRCC5 and XRCC6 were also increased by 1.79-fold (95% CI (1.68, 1.90); q < 0.01) and 1.65-fold (95% CI (1.53, 1.78); q < 0.001), respectively, in ADPKD tissue, and this was maintained in all cyst sizes." (PMID 34638853, 2021).
diabetic nephropathy (1 paper, 2023). "Although, to the best of our knowledge, not much is known about a possible role of the DNA repair proteins, XRCC5 and XRCC6, in the context of diabetic nephropathy." (PMID 36769128, 2023).
granulosa cell tumour (1 paper, 2020). "As FOXL2 is highly expressed in ovarian granulosa cells and plays pivotal roles in ovarian development, the interaction of FOXL2 with XRCC5 and XRCC6 was examined in human ovarian granulosa cell tumour-derived KGN cells." (PMID 32332759, 2020).
HIV-1 infection (1 paper, 2022). The type species of lentivirus and the etiologic agent of acquired immunodeficiency syndrome (AIDS). "In this study, we conducted a case-control study in the northern Han Chinese population to investigate associations of 22 SNPs in XRCC7, XRCC6, XRCC5, XRCC4, and LIG4 genes with the risk of HIV-1 infection and the progression of AIDS." (PMID 36312587, 2022). "In gene-gene interaction analysis, significant SNP-SNP interactions of XRCC6 and XRCC4 genetic variations were found to play a potential role in the risk of HIV-1 infection." (PMID 36312587, 2022). "Positive associations were observed between XRCC6 rs132770 and XRCC4 rs1056503 genotypes and the susceptibility to HIV-1 infection." (PMID 36312587, 2022). "The GMDR method was used to study the association of 10 SNPs in XRCC6 and XRCC4 genes with high-order interactions on HIV-1 infection." (PMID 36312587, 2022). "In addition, in the analysis of SNP-SNP interaction, our results provide evidence for a four-locus interaction between XRCC6 and XRCC4 variants in the risk of HIV-1 infection and further highlight the role of multilocus effects in the genetic component of HIV-1 infection." (PMID 36312587, 2022).
ischemic heart disease (1 paper, 2025). "Fisetin confers cardioprotection by targeting Xrcc6, offering mechanistic insights into DNA repair–immune crosstalk and providing a potential therapeutic strategy for ischemic heart disease." (PMID 41041340, 2025).
lymph node metastasis (1 paper, 2023). "A risk model based on XRCC4, XRCC5 and XRCC6 showed that the risk score was related to the prognosis, gender, clinical stage, T stage, lymph node metastasis and metastasis of LUAD patients and was an independent risk factor for the prognosis of LUAD patients." (PMID 37737707, 2023).
myocardial ischemia (1 paper, 2025). A disorder of cardiac function caused by insufficient blood flow to the muscle tissue of the heart. "In summary, Xrcc6 may promote immune microenvironment remodeling following myocardial ischemia–reperfusion injury by regulating macrophage polarization." (PMID 41041340, 2025).
oropharyngeal tumor (1 paper, 2023).
thymic lymphoma (1 paper, 2025). "C8, C11, C7, and C18 were proximal to double‐positive T cells, representing thymic lymphoma characterised by elevated expression levels of genes like Notch1, Hes1 and Desi1,72, 73 along with markers associated with thymic T‐cell development such as Rag1/2, Xrcc6 and Dntt74." (PMID 40887856, 2025).
cancer (91 papers, 2003 to 2025). A tumor composed of atypical neoplastic, often pleomorphic cells that invade other tissues. "The association between the XRCC6 SNPs and different types of cancer has been investigated in the literature." (PMID 39734356, 2024). "Numerous studies have reported that SNPs of XRCC6 are associated with genetic susceptibility to various cancers, including head and neck, bladder, lung, kidney, prostate, oral, and gastric cancers." (PMID 37679817, 2023). "Genetic polymorphisms in the NHEJ gene XRCC6/KU70 are associated with several kinds of cancers; however, several contrasting results are reported and the effect of KU70 polymorphisms on cancer risk is still ambiguous." (PMID 32656256, 2020). "Functional studies are also needed to elucidate the roles of XRCC6 promoter polymorphisms in cancer pathogenesis." (PMID 25569644, 2015). "In conclusion, this meta-analysis showed some evidence of the XRCC6 SNP polymorphisms and cancer risk, supporting the existence of association between XRCC6 polymorphisms and cancer risks in different ethnicities and cancer types." (PMID 25569644, 2015). "In this study, we performed a systematic review of association between XRCC6 polymorphisms and cancer risks based on 20 case–control studies." (PMID 25569644, 2015). "A number of studies have been carried out to investigate the association of X-ray repair complementing defective repair in Chinese hamster cells 6 (XRCC6) polymorphisms and cancer risks, and the results remained inconsistent and inconclusive." (PMID 25569644, 2015). "In overall comparison, there was obvious evidence of an association between XRCC6 rs2267437 polymorphism and increased cancer risk (GG vs. CC: OR = 1.33; 95% confidence intervals (CI), 1.09–1.62; recessive model (GG vs. CC/CG): OR = 1.21; 95% CI 1.00–1.47)." (PMID 25569644, 2015). "Summary odds ratios and corresponding 95% confidence intervals for XRCC6 polymorphism and cancer risk were estimated using fixed- or random-effects models when appropriate." (PMID 25569644, 2015). "The results confirmed the association of PC4 with XRCC5/XRCC6 in relevant cancer and normal cells." (PMID 37437887, 2023). "Overall, the results provided evidences that the single nucleotide polymorphisms in XRCC6 promoter region might play different roles in various cancers, indicating different cancers have different tumorigenesis mechanisms." (PMID 25569644, 2015). "To assess the effect of XRCC6 polymorphisms on cancer susceptibility, we conducted a meta-analysis, up to May 23rd 2014, 6267 cases with different types of tumor and 7536 controls from 20 published case–control studies." (PMID 25569644, 2015). "Altered activities of NHEJ genes including XRCC5/KU80, XRCC6/KU70, PRKDC/DNA-PKcs, and TP53BP1 can be either negatively or positively associated with platinum resistance, depending on types of cancer cell lines or clinical samples." (PMID 34645978, 2021). "For example, the methylation regions located in ACAA2, NUSAP1, OGFOD1, PSMD5, SNRNP40, USP37 and XRCC6 are shared by five cancers (i.e., BRCA, CESC, COAD, KIRP and SARC)." (PMID 34464378, 2021). "DNA polymorphism such as studies on single nucleotide polymorphisms (SNPs) and variable number of tandem repeats (VNTRs) at NHEJ repair genes (XRCC5, XRCC6 and XRCC7) are associated with an increased risk of radiation sensitivity and cancer." (PMID 33685509, 2021). "X-ray repair cross-complementing proteins (XRCC1 and XRCC6), which recruit several DNA damage response proteins and plays key role in DNA repair and cancer progression." (PMID 33251127, 2020). "Additionally, XRCC6 expression correlated with sensitivity to several anti-cancer drugs and tumor stemness." (PMID 39769336, 2024). "Moreover, we investigated the correlation between XRCC6 expression and prognosis in cancer patients." (PMID 39446493, 2024). "Strikingly, XRCC6 exhibited high expression in T/NK cells of LUAD cancer." (PMID 39446493, 2024).